EPOR (erythropoietin receptor)
Diseases named in the same sentence as EPOR in open-access papers (continued):
Sharing a sentence is not in itself a finding about the gene and the disease.
tumor (continued). "Phosphorylation of JAK2 or STAT5 in tumor cell lines with rHuEpo, molecules more specific to the EpoR signaling pathway, was rarely reported." (PMID 23861852, 2013). "We wished to compare EpoR protein expression in normal and tumor tissues using specific and sensitive anti-EpoR antibodies." (PMID 23861852, 2013). "In contrast to the western data with the tumor tissues above, in an earlier study, EpoR was detected in ∼ 10% of 60 different tumor cell lines derived from numerous tissue sources, but levels were still over 20-fold below that of positive controls." (PMID 23861852, 2013). "In the present work we analyzed the gene expression of EPO and its cognate receptor (EpoR) in a rat model of thioacetamide-induced damage and tumor." (PMID 23052842, 2013). "To determine the clinical relevance of tumor tissue EPOR expression, we performed comparative statistical analysis of bronchial brush EPOR mRNA expression and clinicopathological variables." (PMID 24155958, 2013). "Tumor xenograft of 786-0 cells with knockdown EpoR grew significantly slower than the xenografts of the two control groups." (PMID 23028796, 2012). "Our findings suggested that Epo/EpoR pathway was involved in, at least partially, promoting cell proliferation and invasiveness, and reducing cell apoptosis and sensitivity to anti-tumor drug Sunitinib in RCC." (PMID 23028796, 2012). "The direct proliferative effect of rhEPO seems to be EPOR-dependent and tumor cell specific, because previous studies have shown that growth response to rhEPO is only on those cells expressing cell-surface EPOR." (PMID 22086127, 2012). "Several studies have suggested that tumour tissues and tumour cell lines express EpoR mRNA and also contain EpoR protein as demonstrated by western-blot analysis or immunohistochemistry." (PMID 22395661, 2012). "For example, studies examining EpoR-mRNA levels often used bulk tumour tissue, which can contain stromal cells and other cell types that infiltrate from blood." (PMID 22395661, 2012). "Their potential direct impact on tumor cells was assessed by studying i) the expression of EpoR in PDAC cells, ii) Epo-induced down-stream signaling, and iii) functional consequences of exposure to Epo." (PMID 21829709, 2011). "Several immunohistochemistry studies using polyvalent rabbit anti-sera raised against EpoR (i.e., polyclonal antibodies for EpoR) have reported EpoR expression in some primary human tumours and endothelial cells." (PMID 20051958, 2010). "Copy numbers of EPOR were between 0.5 and 1.5 in all tumour samples, except one tumour with a copy gain and one with a copy deletion." (PMID 18349818, 2008). "Taken together, these results demonstrated that the EPOR locus was rarely amplified in primary human tumours." (PMID 18349818, 2008). "Although the EPOR locus was rarely amplified in tumours, it was possible that EPOR was overexpressed through other mechanisms." (PMID 18349818, 2008). "Levels of EPOR transcripts were further examined in microarray analyses of 121 tumour and 170 normal tissues." (PMID 18349818, 2008). "In this analysis, we found that levels of EPOR transcripts in tumour samples and cell lines from more than 15 different tumour types were equivalent to, or lower than, levels in normal tissues." (PMID 18349818, 2008). "Here, we report the first comprehensive, quantitative analysis of EPOR transcript levels in multiple tumour types compared to tissues of tumour origin." (PMID 18349818, 2008). "To investigate the potential for EpoR to be overexpressed in tumours, we have evaluated human tumours for amplification of the EPOR locus, levels of EPOR transcripts, and expression of surface EpoR protein." (PMID 18349818, 2008). "Genomic analysis of 1083 tumours showed that the EPOR locus was amplified in <0.7% tumours, only in large amplicons, and less than 2–3 times the normal copy number." (PMID 18349818, 2008).
tumor (continued). "Representational oligonucleotide microarray analysis and CGH data from 1083 tumour samples from 15 different tumour types were analysed for amplification of the EPOR locus." (PMID 18349818, 2008). "Comparative analysis of EPOR transcription in tumour vs non-tumour tissues determined that transcript levels in kidney, stomach, colon, and lung tumours and cell lines were lower than those found in corresponding normal tissues." (PMID 18349818, 2008). "We have demonstrated that the Epo/EpoR system is involved in NB angiogenesis and that expression of Epo in tumour cells and of EpoR in endothelial cells increases in parallel with grade of malignancy and is highly correlated with the extent of angiogenesis." (PMID 17394500, 2007). "The presence of an autocrine-paracrine Epo–EpoR system in tumours and the possible effects of Epo on tumour microenvironment and angiogenesis are consistent with a complex biology for Epo–EpoR signalling in cancer." (PMID 17394500, 2007). "In keeping with this observation, Epo/EpoR expression in tumour and endothelial cells, respectively, was also highly correlated with the extent of angiogenesis and higher clinical stage." (PMID 17394500, 2007). "Regarding differences in microvessel, Epo and EpoR expression in both endothelial and tumour cells, the within-group comparison showed that both counts were always significantly correlated." (PMID 17394495, 2007). "Co-injection of erythropoietin with tumor cells or expression of EPOR-R129C in tumor cells significantly stimulated tumor neovascularization and growth in window chambers." (PMID 17579721, 2007). "The aim of this study was to correlate microvascular density and Epo/Epo-receptor (EpoR) expression in endothelial and tumour cells to the clinical stage of NB." (PMID 17394500, 2007). "We find that local rEPO treatment in window chambers or stable expression of a constitutively active EPOR mutant (EPOR-R129C) in tumor cells promotes the induction of tumor angiogenesis and stimulates growth." (PMID 17579721, 2007). "The presence of an autocrine-paracrine Epo–EpoR system in tumours and the possible effects of Epo on the tumour microenvironment and angiogenesis are consistent with a complex biology for Epo–EpoR signalling in cancer." (PMID 17394495, 2007). "Co-injection of erythropoietin antagonist proteins (soluble EPOR or anti-EPO antibody) with tumor cells or stable expression of antagonist R103A-EPO protein secreted from tumor cells inhibited angiogenesis and impaired tumor growth." (PMID 17579721, 2007). "The correlation of Epo/EpoR expression with angiogenesis and tumour progression suggests the presence of a loop in the Epo–EpoR system." (PMID 17394500, 2007). "In this study, we correlated Epo/EpoR expression with vascular density across the whole spectrum of neuroblastic tumours reflecting different clinical stages." (PMID 17394500, 2007). "Poorly differentiated HCC had a higher degree of vascularization than other stages and Epo/EpoR expression in both tumour and endothelial cells increased in parallel with grade of malignancy and was highly correlated with the extent of angiogenesis." (PMID 17394495, 2007). "Tumor growth rate was significantly increased in animals injected with cells expressing EPOR-R129C compared to the growth rate in animals injected with negative control cells (P<0.001)." (PMID 17579721, 2007). "Regarding differences in microvessel, Epo and EpoR expression in both endothelial and tumour cells, within-group comparison showed that both counts were always significantly correlated." (PMID 17394500, 2007). "To establish relevance for this study, we determined the EpoR status of each of the four tumour cell lines used." (PMID 16288305, 2005). "However, concerns have been raised about the potential promotion of tumour growth and metastasis by activating signalling pathways mediated by EPOR." (PMID 41514679, 2026).
tumor (continued). "Additionally, EPOR expression levels outside the erythroid compartment—including on tumor cells—are extremely low." (PMID 41268443, 2025). "While increased EPO levels may initially enhance oxygen delivery via increased red blood cells, tumor cells can develop functional EPOR." (PMID 38542288, 2024). "Additionally, the mesenchymal characteristics of GBM are mediated by the EPO secreted by GBM, which can act on the EPOR of microglia and oligodendrocytes in the microenvironment, promote tumor survival, proliferation, and angiogenesis." (PMID 37692522, 2024). "The expression of EPOR has been demonstrated in a panel of 29 tumor cell lines and may be related to increased resistance of cancer cells to various therapies." (PMID 37239828, 2023). "A drawback of prolonged and/or high dose Epo administration is the overproduction of erythrocytes leading to increased risk of thrombosis, stimulation of cancerogenic cell proliferation and tumor vascularization all resulting from activation of homodimeric classical EpoR." (PMID 37168680, 2023). "To test this hypothesis, we generated EPOR-knockdown cancer cells to grow tumor xenografts in mice and analyzed tumor cellular respiration via high-resolution respirometry." (PMID 36052260, 2022). "Besides the well-established role of mutated/dysregulated c-kit in cancer, current evidence suggests that a functional interaction between c-kit and EPOR increases cancer cell migration, thereby promoting tumor progression." (PMID 35694408, 2022). "Thus, our data imply that EPOR not only stimulates tumor growth but also regulates tumor metabolism and is a target for direct intervention against progression." (PMID 36052260, 2022). "Therefore, in the study, we aimed to explore the feasibility of EPOR as a prognostic marker and its role in tumor immunity, tumor occurrence, and progression through bioinformatics techniques." (PMID 35359375, 2022). "In addition, EPOR expression in PCPG correlated more strongly with tumor purity, and the correlation was stronger (r = 0.351)." (PMID 35359375, 2022). "Furthermore, we found significant differences in EPOR expression in different tumor stages of BLCA, KICH, and PAAD, with enhanced specificity in erythroid cells, hepatic stellate cells, and Hofbauer cells." (PMID 35359375, 2022). "Our study suggests that an approach that solely targets EPOR in cancer cells may help control tumor metabolism and thereby the malignancy of tumors in human patients." (PMID 36052260, 2022). "Although EPO treatment of wild-type A549 tumor-bearing mice did not alter tumor growth or respiratory control, the loss of EPOR per se reduced tumor growth and mitochondrial density with an unabated respiratory potential." (PMID 36052260, 2022). "EPOR signaling has been proved critical to tumor survival and proliferation." (PMID 32015330, 2020). "There are many studies demonstrating that EPO/EPOR signalization in cancer cells can: induce cell proliferation, change the sensitivity to chemotherapeutics, induce angiogenesis and/or tumor neovascularization." (PMID 30606107, 2019). "It seems that this problem is more complex and therefore we have decided to focus on EPOR expression at several levels such as the role of methylation in the regulation of EPOR expression, identification of possible EPOR transcripts and the presence of EPOR protein in selected tumor cells." (PMID 30606107, 2019). "We next investigated if EPOR regulates migration and invasion in tumor cell lines." (PMID 28418910, 2017). "Local blockage of EPO signaling could suppress the growth of dual EPO and EPOR-positive NSCLC tumor and prolong survivals of xenograft mice." (PMID 29137269, 2017). "One way, by which Epo could trigger tumor growth, is its direct effect on the tumor cells via the EpoR." (PMID 27543111, 2016). "The available literature data suggest that Epo/EpoR may play an important role in tumor progression." (PMID 27543111, 2016).
tumor (continued). "Thus, treatment with Epo stimulated the growth of EpoR-positive tumor of DLD-1 xenografts by promoting angiogenesis." (PMID 27543111, 2016). "EpoR expression in tumor vascular endothelium suggests that Epo may affect the tumor microenvironment by enhancing vessel formation." (PMID 27543111, 2016). "This indicates that EPO might not only have an effect on erythroid progenitor cells, but also could induce EPO-mediated survival signaling in other cells expressing the EPOR, including tumor cells." (PMID 27494133, 2016). "In vivo Epo antagonism studies have reported that the blockade of Epo:EpoR inhibited tumor growth." (PMID 25807104, 2015). "On the one hand, binding of exogenous rhEPO with EPOR might prevent or stabilize tumor progression by decreasing hypoxia through increasing oxygenation (erythrocytosis)." (PMID 26210994, 2015). "In contrast, no rHuEpo-mediated activation of pERK, pAKT, or the canonical EpoR pathway constituent, pSTAT5, was observed in any of the tumor samples that were analyzed at any concentration of rHuEpo (the highest concentration employed, 300 U/mL, is represented)." (PMID 25807104, 2015). "An alternative hypothesis is that ESAs may directly increase tumor cell proliferation and survival by activating EpoR on tumor cells." (PMID 25807104, 2015). "Accordingly, it could be important to evaluate whether silencing EPOR on these GSC could also improve the efficacy of conventional treatment on these pool of tumour cells." (PMID 25544764, 2015). "Studies suggest that EpoR-protein levels are very low in tumors and tumor-cell lines." (PMID 24337485, 2014). "Potentially explaining these observations, it has been hypothesized that ESAs could bind and activate EpoR on tumor cells to promote their growth and/or survival or stimulate EpoR on endothelial cells to promote tumor angiogenesis." (PMID 24337485, 2014). "As EPOR is present in various cancer cells, the use of rHuEPO in cancer patients may be problematic due to potential activation of EPO-EPOR signaling pathways resulting in tumor protection (anti-apoptotic action) or proliferation (mitogenic action)." (PMID 25426117, 2014). "Possible imbalances in regards to tumor site, nodal involvement, erythropoietin receptor or radiation may – if at all - favor patients with weak PSMD1-expression scores." (PMID 24593279, 2014). "Second, studies are described that investigated whether erythropoiesis-stimulating agents could stimulate tumor progression in cancer patients and whether EpoR is expressed and functional on tumor cells or on endothelial cells." (PMID 24337485, 2014). "Furthermore, increased EPOR expression was identified as prognostic factor for reduced overall survival, more aggressive tumor behavior, and progression-free survival." (PMID 25426117, 2014). "Detailed information will then be presented on techniques used to examine specific aspects of EpoR expression, function, and hypothesized roles in tumor progression/angiogenesis." (PMID 24337485, 2014). "One hypothesis is that Epo or exogenous ESAs could stimulate tumor growth by activating EpoR on endothelial cells to facilitate angiogenesis near tumors." (PMID 24337485, 2014). "However with this study we cannot eliminate the possibility that rare tumor types or rare cells within tumors express high levels of EpoR." (PMID 23861852, 2013). "Given that A82 can specifically detect low levels of human EpoR by western analysis, it was used to determine if EpoR could be detected in human tumor biopsies." (PMID 23861852, 2013). "PDGFR, VEGFR and EPOR are also known to be activated by tumor hypoxia." (PMID 23675504, 2013). "It has been postulated that, if tumor cells express EpoR, erythropoiesis-stimulating agents could activate these receptors to induce tumor cell proliferation." (PMID 23052842, 2013). "Therefore, we normalized tumor tissue EPOR expressions to the patient-matched normal endobronchial EPOR expression levels (T/N)." (PMID 24155958, 2013).
tumor (continued). "In addition, the only two studies on the prognostic value of EPOR expression in human NSCLC samples were based on tumor immunohistochemistry data generated with anti-EPOR antibodies the specificity of which has been questioned so far." (PMID 24155958, 2013). "The effect may be induced through interaction with tumor cell EPO receptors (EPOR), which when activated promote the tumor vascularization required for adequate oxygenation." (PMID 24004818, 2013). "To address the role of c-Myc, we investigated whether subcutaneous (s.c) inoculation of transduced Ba/F3 cells into nude mice could induce tumor formation as well as VF/EpoR cells." (PMID 23300995, 2013). "Taken together these results raise questions about the hypothesis that most tumors express high levels of functional EpoR protein and that rHuEpo directly stimulates growth/survival of tumor cells." (PMID 23861852, 2013). "The detection of EpoR transcripts in tumor cells lines led to suggestions that rHuEpo may also act as a tumor growth factor and in turn promote tumor progression." (PMID 23861852, 2013). "Iatrogenic effects of rHuEPO via EPOR signaling resulting in potentially accelerated tumor cell proliferation and angiogenesis may, thus, compete with rHuEPO’s beneficial effects." (PMID 24155958, 2013). "Furthermore, EpoR mRNA expression analyzed in the excised tumor was 14.6 ± 2.9-fold higher than in the normal liver." (PMID 23052842, 2013). "Our data provided the evidences that Epo/EpoR system in RCC may be involved in tumor growth, invasion, survival and sensitivity to Sunitinib." (PMID 23028796, 2012). "Furthermore, the univariate analysis revealed that patients with high tumor EPOR expression had a lower 5-year overall survival rate (p = 0.0011) and 5-year disease-specific survival rate (p = 0.0017) than patients who had low tumor levels of EPOR." (PMID 22639817, 2012). "This probably leads to tumor necrosis and hypoxia in the microenvironment of tumor and may result into the higher level of EPOR." (PMID 22639817, 2012). "It has been postulated that if tumour cells express EpoR, ESAs could activate these receptors to induce tumour cell proliferation." (PMID 22395661, 2012). "The results demonstrate that, in HNSCC cells expressing functional EpoR, rhEpo promotes invasion, cell proliferation, and induces resistance to cisplatin, which may contribute to tumor progression." (PMID 22188703, 2011). "Since we succeeded in proving EpoR expression at the mRNA and protein level, as well as EpoR initiation of PI3K/Akt signaling in PDAC cells, a direct impact on the tumor cells emerged as a highly probable event to be associated with the negative clinical associations seen in sEpohigh PDAC patients." (PMID 21829709, 2011). "The difference in EpoR expression between the two cell lines may be related to the slightly higher tumor grade of UMSCC-22B." (PMID 22188703, 2011). "Second, the lack of functional consequences could result from the blockade of Epo-binding to EpoR by sol-EpoR secreted by tumor cells." (PMID 21829709, 2011). "Importantly, the finding that the widely used anti-EpoR antibody C-20 cross-reacts with heat-shock protein 70 (HSP70) called into question C-20-based findings of EpoR in tumor cells and tissues." (PMID 21829709, 2011). "The majority of tumor samples expressed mRNA for EPOR, ERBB2, and IGF1R at varying levels." (PMID 21318160, 2010). "Since the findings and conclusions from studies that used C-20 and other anti-EpoR antibodies to detect EpoR are inconclusive, we performed an extensive investigation of the potential for EpoR to be overexpressed in tumour cells through antibody-independent approaches." (PMID 18349818, 2008). "Amplification of EPOR in amplicons <10 Mb was identified in less than 0.7% of tumours (n=8) and was similar to the frequency of amplification of other established non-oncogenic loci such as glyceraldehyde-3-phosphate dehydrogenase (GAPDH), β-actin (ACTB), and β-glucuronidase (GUSB)." (PMID 18349818, 2008).